ERBB2 (erb-b2 receptor tyrosine kinase 2)
Diseases named in the same sentence as ERBB2 in open-access papers (continued):
Sharing a sentence is not in itself a finding about the gene and the disease.
breast cancer (continued). "In solid tumors, ErbB2/HER2 overexpression is a well-known driver of breast cancer as well as colon cancer, and EGFR overexpression is commonly observed in lung cancer and head and neck cancers." (PMID 30087897, 2018). "In the present study, we demonstrate that GroA inhibits the activation of ErbB2 in breast cancer xenografts, and markedly impairs growth of breast cancer tumors in vivo." (PMID 29352243, 2018). "Breast cancer is a heterogeneous disease, characterized into at least four different subtypes: luminal A, luminal B, ERBB2 overexpression, and basal-like." (PMID 30518851, 2018). "SRC-1 expression was found to be significantly increased in breast cancers, and positively correlated with ERBB2 expression, disease recurrence, and poor survival rates." (PMID 29717026, 2018). "For in vitro studies, we continuously cultivated human ERBB2-positive BT474 breast cancer cells in the presence of increasing concentrations (100–300 nM) of lapatinib for 6 months." (PMID 29799521, 2018). "ErbB-2 class receptor binding was enriched in basal cells (q = 0.004), and numerous pathways critical to cell differentiation, survival and breast cancer were enriched in luminal including c-KIT, NOTCH, and GH receptor signaling." (PMID 29921600, 2018). "In breast cancer, it has been shown that ERBB2 amplification is a marker of poor prognostic that can be reversed by the administration of HER2 inhibitors." (PMID 29515767, 2018). "ERBB2 plays a critical role in carcinogenesis and cancer progression and has become a targeted therapeutic molecule in breast cancer and GC." (PMID 30123134, 2018). "Together, our compelling data provide a strong foundation for continued investigation regarding the clinical impact of ganetespib as a promising therapeutic option for patients with ErbB2+ breast cancer." (PMID 29717218, 2018). "The overexpression of ErbB2 was reported to inhibit both the intrinsic and extrinsic pathway of apoptosis in breast cancer." (PMID 30402124, 2018). "treatments targeting the Human Epidermal Growth Factor Receptor 2 (HER2/ERBB2) have improved the natural history of HER2-positive breast cancer." (PMID 30333908, 2018). "We have also shown that ErbB2, a major oncoprotein, downregulates Irf6 in breast cancer cells growing in a 3D manner." (PMID 30545388, 2018). "We explored the function and structure of breast cancer feed arteries and equivalent control arteries based on a murine model of ErbB2-induced breast cancer." (PMID 29566737, 2018). "Nonetheless, the full scope of GroA treatment in breast cancer, alone and in combination with ErbB2 inhibition, is yet to be examined." (PMID 29352243, 2018). "This work has led to the identification of potential druggable kinases in breast cancer, other than ERBB2, and emphasized the advantage of connecting the genome to the proteome." (PMID 29503809, 2018). "In an effort to identify the mechanisms by which ErbB2 blocks breast cancer cell anoikis, we used MCF10A cells, which are spontaneously immortalized highly anoikis-susceptible human nonmalignant breast epithelial cells." (PMID 30545388, 2018). "Using HR (ERα and PR) and ERBB2 status, we also subdivided the total population (n = 456) into four breast cancer molecular subtypes: HR+/ERBB2+ (n = 54), HR+/ERBB2− (n = 289), HR−/ERBB2+ (n = 45) and HR−/ERBB2− (n = 68)." (PMID 29996935, 2018). "The activation of RTK signaling pathways is a driving force of ErbB2+ breast cancer cell proliferation and survival." (PMID 29717218, 2018). "One of the most well-known genes in breast cancer that the extent of its expression is used as a prognostic value is ERBB2 (Harari and Yarden, 2000)." (PMID 29743853, 2018). "In breast cancer 1:5 women have tumours that over express the epidermal growth factor receptor 2 (HER2)/Neu) protein due to amplification of the oncogenic ERBB2 gene." (PMID 29497041, 2018).
breast cancer (continued). "For the STRAT4 ERBB2 to IHC HER2 comparisons, with equivocal breast cancers (IHC 2+ samples) excluded, concordance ranged from 94.3 to 92.8%, and from 93.3 to 91.6% if FISH was employed to resolve the IHC 2+ samples." (PMID 30120700, 2018). "For example, miR-26a/b are reported to target the 3’ UTR of ERBB2 and suppress ErbB2 protein expression in tamoxifen-resistant ER+ breast cancer cells." (PMID 30214383, 2018). "Pyk2 expression is significantly increased in early and advanced breast cancer and co-overexpressed with ErbB-2 in early stages of ductal in situ carcinoma and invasive breast cancer." (PMID 29738483, 2018). "Some ERBB family inhibitors, such as Lapatinib and Afatinib are also developed for treatment of ERBB2+ breast cancer or GC." (PMID 30123134, 2018). "About 30% of breast cancer cases showed ERBB2 up-regulation that has become an important indication of chemoresistance and worse prognosis of breast cancer." (PMID 30126855, 2018). "This study has demonstrated that ERBB2 genomic alterations can be found beyond oesogastric and breast cancers in a wide variety of tumor types at low to moderate frequency (between <1% and 13%)." (PMID 29515767, 2018). "We have reported that ErbB2 inhibits anoikis of breast cancer cells by downregulating the proapoptotic protein Perp." (PMID 30545388, 2018). "For instance, nucleolin binds to a receptor tyrosine kinase (ErbB2) and promotes its activation, resulting in enhancement of tumorigenicity of breast cancer." (PMID 29928487, 2018). "In ERBB2-amplified breast cancer, expression of KCTD21 (Potassium Channel Tetramerization Domain Containing 21) was related to genomic copy number alterations." (PMID 30618566, 2018). "In combination with the fluoropyrimidine capecitabine, lapatinib is more efficient than capecitabine alone in women with ErbB2-positive advanced breast cancer that has progressed after treatment with anthracyclines, taxanes, and trastuzumab." (PMID 29662626, 2018). "Overall, these data support ErbB2 as a client protein of HSP90 and indicate that the selective targeting of ErbB2 is a critical component of the anti-cancer mechanism of ganetespib in ErbB2+ breast cancer cells." (PMID 29717218, 2018). "Marker Cluster 4 genes are enriched in HER2-positive breast cancers and includes ERBB2 (HER2), GRB7 and CEACAM6." (PMID 30279965, 2018). "Taken together, ganetespib-induced apoptosis is mediated by the induction of death receptor and mitochondrial pathways in ErbB2+ breast cancer cells." (PMID 29717218, 2018). "We have further demonstrated that the effect of ErbB2 on Irf6 can be blocked by ErbB2-targeted drugs such as trastuzumab in cultured breast cancer cells and in patients’ tumors." (PMID 30545388, 2018). "IPAD also identified heat-shock protein regulation as a potential therapeutic strategy as noted by the ability of the Hsp90 inhibitor geldanamycin to promote ErbB2 degradation in SKBR breast cancer cells." (PMID 29487713, 2018). "Overall, our data suggest that ganetespib modulates cell cycle regulators to elicit anti-proliferative effects in ErbB2+ breast cancer cells." (PMID 29717218, 2018). "ERBB2/HER2 amplification is actionable in breast cancer and gastric cancer (level 1 evidence, FDA-approved)." (PMID 30442178, 2018). "Consistent with an oncogenic effect, RANBP9 is overexpressed in a similar proportion of breast cancer patients as ERBB2—an important driver of breast cancer (13.04% and 14.13% respectively)." (PMID 30205839, 2018). "Amplification or overexpression of ErbB2 is observed in ∼30% of breast cancer patients, and often drives cellular transformation and cancer development." (PMID 29352243, 2018). "In ErbB2-positive breast cancer cells, the PGC-1α/ERRα complex directly regulates the expression of glutamine metabolism enzymes, leading to the provision of glutamine carbons to de novo fatty acid synthesis." (PMID 29599799, 2018).
breast cancer (continued). "miR-1268b increases breast cancer cell chemosensitivity via modulation of the PI3K/Akt pathway by targeting ERBB2." (PMID 29710817, 2018). "Breast cancers are classified based on molecular features that include the expression or overexpression of growth factor receptors such as the Erb-B2 receptor tyrosine kinase 2 (ERBB2/HER2), ER, and PgR." (PMID 29415082, 2018). "In this study, we demonstrated the potent anti-cancer effects of ganetespib on ErbB2+ breast cancer cells in vitro and in vivo." (PMID 29717218, 2018). "HER-2 positive breast cancer comprises cancers which exhibit the overexpression or amplification of the Erb-B2 Receptor Tyrosine Kinase 2 (ERBB2) gene (also known as the HER2 protein) and accounts for approximately 20% of all breast cancers." (PMID 30071039, 2018). "AQP3 has proven to serve as a potential prognostic marker after curative surgery in early breast cancer demonstrating human epidermal growth factor receptor 2 (HER2/neu, c-erbB2) overexpression." (PMID 30555637, 2018). "Over the course of one year, mammary tumors only arose in recipient mice receiving ErbB2;Fsp-cre;Ptenfl/fl donor epithelium, suggesting a permanent, pro-tumorigenic effect elicited by neighboring PTEN-null stroma prior to injection." (PMID 30018330, 2018). "In order to evaluate the role of ErbB2 in the modulation of SOCE, we used SK-BR-3 cells that are derived from a pleural effusion of a breast cancer overexpressing ErbB2." (PMID 29662626, 2018). "Having established that GroA has a potential as an anti-breast cancer treatment, we were interested in examining the effect of co-inhibiting both ErbB2 and nucleolin." (PMID 29352243, 2018). "In vivo data provided critical evidence that ganetespib inhibits ErbB2-overexpressing mammary tumor growth in MMTV-ErbB2 mice inoculated with syngeneic mammary tumor cells." (PMID 29717218, 2018). "HER2 overexpression or ERBB2 amplification are observed in approximately 20% of metastatic breast cancers and 20% of metastatic oesogastric adenocarcinomas." (PMID 29515767, 2018). "AHR mRNA expression level was weakly associated with ERα and HR negative status (p = 0.039 and p = 0.018, respectively) and HR-/ERBB2- breast cancer subtypes (p = 0.047)." (PMID 29320557, 2018). "The incidence of brain metastasis in patients with metastatic breast cancer varies from 10 to 15% and these rates are as high as 50% in patients with the Erb-B2 receptor tyrosine kinase 2 (ERBB2 or HER2)-positive breast cancer." (PMID 29755676, 2018). "Due to its proximity to the ERBB2 gene, MIEN1 is commonly amplified in breast cancer along with ERBB2 which leads to an overexpression of MIEN1 protein in many breast cancers." (PMID 30286132, 2018). "ErbB2-driven breast tumor cell anoikis resistance is thought to be a prerequisite for breast cancer progression." (PMID 30545388, 2018). "Our data suggest a mechanism-based rationale for the clinical utilization of HSF1 inhibitors for the treatment of lapatinib-resistant ERBB2-positive breast cancer and/or—in combination with lapatinib—to prevent development of lapatinib resistance." (PMID 29799521, 2018). "Our data support targeting HSP90, via ganetespib, as a promising therapeutic strategy for ErbB2+ breast cancer." (PMID 29717218, 2018). "Depletion of WDR5 reduced ErbB2 expression and cooperated with trastuzumab or chemotherapy to reduce ErbB2-positive breast cancer cell growth." (PMID 29925347, 2018). "The use of monoclonal antibodies targeted against ErbB2 has completely revolutionized the treatment of advanced breast cancers overexpressing ErbB2." (PMID 29662626, 2018). "In this study, we showed that inhibition of EGFR and ErbB2 decreased the amplitude of SOCE in breast cancer cell lines (SK-BR-3 cells) and in other cancer or proliferating cells." (PMID 29662626, 2018).
breast cancer (continued). "Integrated DNA and RNA genomic analysis of HER2+ breast cancers, for the majority of cases, reveals that ERBB2 amplifications are presented in the context of chromoanasynthesis involving either chromosome 17 alone, or with other chromosomes." (PMID 30005627, 2018). "ERBB2 gene, an important marker for HER2+ cancer patients, is also included in our predictor set and its expression is restricted to HER2+ breast cancer cell type." (PMID 29433432, 2018). "In particular, we demonstrated that ErbB2-overexpressing cancer cells are preferentially responsive to ganetespib, and that ganetespib significantly potentiates lapatinib-mediated anti-cancer effects in ErbB2+ breast cancer cells." (PMID 29717218, 2018). "Although ErbB2 is a very sensitive HSP90 client protein, studies investigating the effects of ganetespib on ErbB2+ breast cancer are limited." (PMID 29717218, 2018). "Previous studies had demonstrated that EGFR and ERBB2 amplification was associated with sensitivity to lapatinib, which has been licensed for the treatment of HER2+ breast cancer clinically." (PMID 30258362, 2018). "Use of an automated diagnostic platform (GeneXpert®) and assay (Xpert® Breast Cancer STRAT4) that employs RT-qPCR to quantitate ESR1, PGR, ERBB2, and MKi67 mRNAs from formalin-fixed, paraffin-embedded (FFPE) tissues facilitates analyses in less than 3 h." (PMID 30120700, 2018). "The anti-Her-2/neu mimetic peptide recognises the epidermal growth factor ErbB2, which is overexpressed in 30% of breast cancers." (PMID 29385037, 2018). "In 1995, the first peer-reviewed pre-clinical study was reported regarding an adenoviral vector coding antibody gene against HER2 (erbB2), which is a known oncoprotein and a target for breast cancer." (PMID 29949942, 2018). "The assay aims to refine the HER2-positive breast cancer classification taxonomy by including t-erbB2 protein levels as a classifier." (PMID 29872719, 2018). "The cohort (n = 439) was classified into four breast cancer subtypes on the basis of hormone receptor (ERα and PR) and ERBB2 status: HR+/ERBB2+ (n = 50), HR+/ERBB2- (n = 281), HR-/ERBB2+ (n = 41) and HR-/ERBB2- (n = 67)." (PMID 29320557, 2018). "We focused in chromosomal junctions (connections between distant breakpoint of the genome), to investigate how ERBB2 amplifications arise in HER2+ breast cancer." (PMID 30005627, 2018). "BT474 and SKBR3 cell viability was drastically reduced in lapatinib + ganetespib-treated cells as compared to lapatinib treatment or ganetespib treatment alone, indicating synergistic inhibitory effects on ErbB2+ breast cancer cell viability." (PMID 29717218, 2018). "Our results demonstrated that ganetespib stimulates striking growth inhibition and apoptosis in ErbB2+ breast cancer cells." (PMID 29717218, 2018). "This fact correlates to the cross-cancer effect of lung adenocarcinoma to breast cancer and gastric cancer, for which ERBB2 is actionable." (PMID 30442178, 2018). "Lapatinib is approved for use in combination with other anticancer agents for the treatment of the woman with ErbB2 (Her2)-positive breast cancers." (PMID 29740279, 2018). "When mice harboring mammary tumors overexpressing the ERBB2 gene were crossed with CDK4 knockout mice, the resulting littermates did not develop tumors, and the acute loss of cyclin D1 or CDK4 proteins mediated via RNA interference attenuated tumor growth." (PMID 30443290, 2018). "With respect to gene expression, breast cancer is classified into 5 subtypes namely luminal A, luminal B, basal-like (also known as triple negative breast cancer), ERBB2+, and normal breast-like subtype." (PMID 29732012, 2018). "Amplification of the ERBB2 (HER2) oncogene is one of the most clinically relevant genetic changes in breast cancer." (PMID 29930756, 2018).
breast cancer (continued). "Even though the fusion gene had been identified in breast cancer patients, the copy number amplicon (the one harboring the independent ERBB2 and GRB7 genes) had previously been reported in other cancer types, including gastric cancer." (PMID 29414922, 2018). "The integration of our results suggests that the simultaneous regulation of multiple pathways and preferential sensitivity in ErbB2+ breast cancer cells makes ganetespib a promising therapeutic agent for refractory ErbB2+ breast cancers." (PMID 29717218, 2018). "Although previous reports indicate that HSP90 client proteins include ErbB2, Akt, Src, and GSK312,13,21,40, results from this study underscore the multi-level actions of ganetespib on RTK signaling in ErbB2+ breast cancer cells." (PMID 29717218, 2018). "Trastuzumab (Herceptin®) is currently used for the treatment of ErbB2 overexpressing breast cancer and HER2/ErbB2 overexpressing metastatic gastric or gastroesophageal junction adenocarcinoma." (PMID 29342116, 2018). "In trastuzumab-resistant ErbB2-positive breast cancer cells, increased glycolytic activity is mediated by heat shock factor 1 and LDHA and inhibition of glycolysis with 2-DG and the LDH inhibitor oxamate resensitizes resistant cells to trastuzumab." (PMID 30456204, 2018). "Ganetespib potently inhibited cell proliferation, cell cycle progression, survival, and activation/phosphorylation of ErbB2 and key downstream effectors in ErbB2+ breast cancer cells." (PMID 29717218, 2018). "In the present study, we investigated the effects of ganetespib on ErbB2+ breast cancer cells with mechanistic insight." (PMID 29717218, 2018). "Ultimately, our results support the application of ganetespib-mediated HSP90 inhibition as a promising therapeutic strategy for ErbB2+ breast cancer." (PMID 29717218, 2018). "Another example is the ERBB2 tyrosine kinase signalling receptor, which is often found as alternatively spliced in breast cancer as the ∆16HER2 isoform." (PMID 29848666, 2018). "As shown in a mouse model of HER2+ (Erb-B2 Receptor Tyrosine Kinase 2) breast cancer, a permissive effect is also attributed to TAMs for the entry into the bloodstream of circulating tumor cells (CTC)." (PMID 29584702, 2018). "First, we tested the effect of ganetespib in vivo, using R172H/+;ERBB2 mice with mammary tumors that have been previously treated with lapatinib until they acquired resistance, i.e., lapatinib no longer suppressed their growth." (PMID 29799521, 2018). "To validate our in vitro findings that ErbB2-overexpressing cancer cells are highly sensitive to ganetespib, we tested the effects of ganetespib on ErbB2-overexpressing mammary tumor growth in vivo." (PMID 29717218, 2018). "HER2-enriched breast cancer is a complex disease characterized by the overexpression of the ERBB2 amplicon." (PMID 30364267, 2018). "Amplifications such as ERBB2 in HER2+ breast cancer also arise from structural rearrangements and can be examined using comprehensive sequencing technologies such as MPseq and RNAseq." (PMID 30005627, 2018). "Our findings provide fundamental evidence supporting future preclinical and clinical testing of ganetespib in ErbB2+ breast cancer." (PMID 29717218, 2018). "Unfortunately, initial response to trastuzumab is observed in less than 35% of patients with ErbB2 positive breast cancers." (PMID 29662626, 2018). "As such, targeting ErbB2+ breast cancer with HSP90 inhibitors, such as ansamycin and its derivatives, has been tested in previous studies." (PMID 29717218, 2018). "Moreover, by analyzing data from breast cancer patients, obtained from the Cancer Genome Atlas (TCGA) network, we have found that patients who present with both nucleolin- and ErbB2-positive tumors are at greater disease risk and exhibit lower survival rates compared to ErbB2-positive patients." (PMID 29352243, 2018).